ENC1 (ectodermal-neural cortex 1)
Description:
Actin-binding protein involved in the regulation of neuronal process formation and in differentiation of neural crest cells. Down-regulates transcription factor NF2L2/NRF2 by decreasing the rate of protein synthesis and not via a ubiquitin-mediated proteasomal degradation mechanism.
Synonyms: ENC-1; KLHL37; NRPB; PIG10; TP53I10; KLHL35
Tractability: Small molecule: it belongs to a druggable protein family. PROTAC: UniProt records ubiquitination sites on it; ubiquitination databases record sites on it; its protein half-life has been measured.
Gene: Protein-coding gene on chromosome 5 (74,627,406 to 74,641,424, reverse strand). Ensembl gene ENSG00000171617.
Subcellular location: Nucleus matrix; Cytoplasm; Cytoplasm, cytoskeleton
Subcellular location (Human Protein Atlas): Plasma membrane
Gene Ontology:
Molecular function: protein binding; ubiquitin-like ligase-substrate adaptor activity
Biological process: negative regulation of translation; proteasomal ubiquitin-independent protein catabolic process; protein ubiquitination; nervous system development; proteasome-mediated ubiquitin-dependent protein catabolic process; ubiquitin-dependent protein catabolic process; positive regulation of neuron projection development; protein catabolic process
Cellular component: Cul3-RING ubiquitin ligase complex; cytoplasm; nucleus; chromatin; cytoskeleton; neuronal cell body; nuclear matrix; nucleoplasm
Genetic constraint (gnomAD): Loss-of-function variants: 19 observed, 42.72 expected, observed/expected ratio (o/e) 0.44, 90% interval 0.31 to 0.65. The upper end of that interval is the gene's LOEUF score, 0.65, which puts it in group 2 of 6, group 1 being the genes least tolerant of losing a copy. Missense variants: 479 observed, 773.97 expected, observed/expected ratio (o/e) 0.62, 90% interval 0.57 to 0.67. Synonymous variants: 285 observed, 307.16 expected, observed/expected ratio (o/e) 0.93, 90% interval 0.84 to 1.02.
Homologues: Orthologues: chimpanzee ENC1 (99% identical), dog ENC1 (99% identical), macaque ENC1 (99% identical), pig ENC1 (99% identical), guinea pig ENC1 (99% identical), rabbit ENC1 (99% identical), rat Enc1 (99% identical), mouse Enc1 (99% identical), tropical clawed frog enc1 (93% identical), zebrafish enc1 (89% identical), Drosophila melanogaster gprs (15% identical). Paralogues in human: KLHL25 (75% identical), BTBD17 (14% identical).
Diseases named in the same sentence as ENC1 in open-access papers:
ENC1 is named in the same sentence as 61 diseases in open-access papers, as found by Europe PMC text mining. Sharing a sentence is not in itself a finding about the gene and the disease. The quoted sentences say what the papers report.
colorectal carcinoma (11 papers, 2006 to 2025). A malignant epithelial neoplasm that arises from the colon or rectum and invades through the muscularis mucosa into the submucosa. "Numerous studies have shown that ENC1 is overexpressed in various types of cancers, including breast, lung, pancreatic, and colorectal cancer, and its upregulation is correlated with a poorer prognosis." (PMID 38177640, 2024). "Moreover, previous studies have shown that ENC1 promotes the progression of colorectal cancer through JAK2/STAT5/AKT axis-mediated epithelial-mesenchymal transition and stemness." (PMID 35992347, 2022). "As previous study supported that ENC1 may function as an oncogene by mediate Wnt/β‐catenin pathway in colorectal carcinomas." (PMID 32618411, 2020). "Given that ENC1 could up‐regulate the β‐catenin in colorectal carcinomas and that β‐catenin pathway regulates the metastasis of breast cancer, we thus have been suggested that ENC1 may promote breast cancer metastasis via up‐regulating the β‐catenin pathway." (PMID 32618411, 2020). "ENC1 is regulated by the beta-catenin/Tcf pathway and up-regulated in colorectal cancer where it may suppress differentiation of colonic cells." (PMID 16919171, 2006). "Ectodermal-neural cortex 1 (ENC-1), which is a component of the TCF/β-catenin complex, is another new target that is up-regulated in colorectal carcinomas." (PMID 20515496, 2010). "Among the up-regulated genes in colorectal cancer, we found 14 genes involved in signal transduction (TDGF1 and ENC1), transcription (SOX9, MYC, and HGFR/MET), nuclear transport (NUP62, NUPL1, NUP155, KPNA2, RANBP5, CSE1L/CAS, NTF2, and RANBP1) and cellular transport (SLCO4A1)." (PMID 16919171, 2006).
breast carcinoma (6 papers, 2020 to 2025). "A meta-analysis has shown that ENC1 is overexpressed in breast cancer (BC) and that this gene is associated with radiation reactions." (PMID 38177640, 2024). "Increased ENC1 expression is a potential diagnostic indicator in individuals with breast cancer and is associated with a poor prognosis." (PMID 38177640, 2024). "Next, analysis by both univariate and multivariate cox regression revealed that the OS time of breast cancer patients was also associated with ENC1 expression except for lymph node metastasis and distant metastasis in TCGA database." (PMID 32618411, 2020). "ENC1 is supposed to become another novel diagnostic, metastatic and prognostic biomarker even a target for breast cancer in the future." (PMID 32618411, 2020). "The results indicated that high ENC1 expression (median as the cut‐off) was associated with wore prognosis among breast cancer patients." (PMID 32618411, 2020). "Altogether, these data demonstrated that ENC1 had a diagnostic accuracy for breast cancer patients and also supported the potential value of ENC1 in breast cancer metastasis and prognosis." (PMID 32618411, 2020). "The present study found that high ENC1 expression caused the high metastasis abilities of breast cancer cells, which was consistent with the finding that ENC1 was associated with invasiveness of both pituitary null cell adenoma and oncocytoma." (PMID 32618411, 2020). "Altogether, ENC1 is significantly overexpressed among breast cancer and had the moderately diagnostic and prognostic value in breast cancer." (PMID 32618411, 2020). "ENC1 overexpression was associated with high metastasis and predicted a poor prognosis in patients with breast cancer." (PMID 32618411, 2020). "Given that the analysis above verified that ENC1 was associated with breast cancer metastasis, then we explored the role of ENC1 in cancer‐associated mortality by using transwell assay." (PMID 32618411, 2020). "In breast cancer, ENC1 overexpression has been linked to increased bone and brain metastases, and may impact the prognosis of cancer by altering tumor cell sensitivity." (PMID 38177640, 2024). "The AUC value is 0.711, revealed the moderate diagnostic value of ENC1 in breast cancer (P < 0.01)." (PMID 32618411, 2020). "Notably, high expression levels of ENC1 were associated with unfavourable prognosis and high metastasis in breast cancer." (PMID 32618411, 2020). "Importantly, high ENC1 expression was associated with high metastasis in breast cancer." (PMID 32618411, 2020). "Inhibiting ENC1 in breast cancer cells can inhibit cell proliferation, migration, invasion, and colony formation." (PMID 38177640, 2024). "To clarify the regulatory signaling pathway of ENC1, we accessed the Ivshina breast cancer dataset, the Schmidt breast dataset, and the Esserman breast dataset from the Oncomine database, respectively." (PMID 34362881, 2021). "This research was set to examine the modulation of ectodermal-neural cortex 1 (ENC1) in radio-resistance in breast carcinoma (BC)." (PMID 34362881, 2021). "The expression and prognosis value of ENC1 expression among breast cancer and normal breast tissue were investigated in The Cancer Genome Atlas database and human samples." (PMID 32618411, 2020). "The present study first verified that ENC1 was overexpressed among breast cancer tissue in comparison with normal breast tissue." (PMID 32618411, 2020). "Analysis of TCGA database revealed the high level of ENC1 expression, indicating the poor prognosis and high metastasis in patients with breast cancer." (PMID 32618411, 2020). "Then, the top 40 genes were analysed as a group to search the potential function of ENC1 in breast cancer." (PMID 32618411, 2020). "We also found knocking down ENC1 in breast cancer will decrease the proliferation, migration, invasion and colony formation of breast cancer cells." (PMID 32618411, 2020).
breast carcinoma (continued). "Next, we analysed the different datasets and identified ENC1 was a special prognosis and metastasis biomarker of breast cancer." (PMID 32618411, 2020). "In the present study, we first discovered that ENC1 was up‐regulated among breast cancer compared with normal breast tissues." (PMID 32618411, 2020). "For further confirming the ENC1 expression panel in breast cancer, IHC was performed with our samples." (PMID 32618411, 2020). "The present study value the feature, clinical significance and the molecular mechanisms of ENC1 in breast cancer." (PMID 32618411, 2020). "Further experiments show ENC1 knockdown inhibited cell proliferation and colony formation of both breast cancer cell lines." (PMID 32618411, 2020). "ENC1 expression between normal breast tissues and breast cancer tissues in TCGA dataset was investigated." (PMID 32618411, 2020). "In addition, further study towards the relationship between ENC1 and breast cancer cell special molecular such as HER2 and BRCA1 is essential." (PMID 32618411, 2020). "These controversial roles of ENC1 drive our interests into the unknown function of ENC1 in breast cancer." (PMID 32618411, 2020). "Additionally, the ENC1 staining in high‐grade breast cancer (HG) was much stronger than that in low‐grade breast cancer (LG)." (PMID 32618411, 2020). "ENC1 was knockdown to explore its function in various breast cancer cell lines." (PMID 32618411, 2020). "Consist with our hypothesis, the expression of ENC1 and β‐catenin was positively correlated in breast cancer among TCGA database and GEPIA." (PMID 32618411, 2020). "ENC1 Knockdown inhibits the growth, clone formation, migration and invasion of breast cancer cells." (PMID 32618411, 2020). "Our study emphasizes that ENC1 is a potential prognostic and metastasis‐related marker of breast cancer, and may function as a possible therapeutic target against breast cancer." (PMID 32618411, 2020). "Moreover, the ENC1 expression level in breast cancer was significantly higher compared with it in matched normal breast tissues." (PMID 32618411, 2020). "We observed that ENC1 was overexpressed in breast cancer tissues." (PMID 32618411, 2020). "Altogether, these results indicated that ENC1 may enhance metastasis by mediating β‐catenin pathway in breast cancer." (PMID 32618411, 2020). "Collectively, these results indicated an oncogenic role of ENC1 in breast cancer." (PMID 32618411, 2020). "ENC1 knockdown inhibited the breast cancer cells' malignant biological properties." (PMID 32618411, 2020). "Thus, ENC1 may potentially contribute to the development of breast cancer through the Wnt/β-catenin signaling pathway." (PMID 38177640, 2024). "We thus suspect ENC1 may also promote breast cancer though Wnt/β‐catenin pathway." (PMID 32618411, 2020). "But the role of ENC1 in breast cancer has not been investigated." (PMID 32618411, 2020). "Given that the expression of ENC1 was higher in breast cancer cell lines in comparison with breast non‐tumorigenic cell line, we performed knockdown experiments in breast cancer cell lines MCF‐7 and MDA‐MB‐231 to illustrate the malignant biological function of ENC1." (PMID 32618411, 2020).
cognitive decline (5 papers, 2017 to 2024). "Moreover, rs76662990G was associated with slower cognitive decline in multiple cognitive domains, which is consistent with widespread expression of ENC1 in the mammalian neocortex." (PMID 28441426, 2017). "In secondary analyses, we explored the mechanism of these associations and found that ENC1 may be related to the previously documented effect of depression on cognitive decline, while UNC5C may alter the composition of presynaptic terminals." (PMID 28441426, 2017).
Alzheimer disease (4 papers, 2022 to 2024). A progressive, neurodegenerative disease characterized by loss of function and death of nerve cells in several areas of the brain leading to loss of cognitive function such as memory and language. "Findings from ENC1, UNC5C, and TMEM106B converged to suggest a possible role in determining cognitive resilience in the aging population affected by Alzheimer's disease, stroke and other NDs." (PMID 39351424, 2024). "For example ENC1, UNC5C, and TMEM106B have been suggested as determinants of cognitive resilience in the aging population affected by Alzheimer's disease, stroke and other neuropathologies." (PMID 39351424, 2024).
cervical cancer (4 papers, 2022 to 2025). A primary or metastatic malignant neoplasm involving the cervix. "Importantly, LOXL1-AS1 increases ENC1 expression through sequestering miR-423–5p in cervical cancer." (PMID 39136001, 2024). "Besides, miR-423–5p acts as a tumor-inhibitor while ENC1 works as a tumor-facilitator in cervical cancer, promoting proliferation and metastasis of this type of cancer cells through activation of the mitogen-activated protein kinase/extracellular signal-regulated kinase (MEK/ERK) and MAPK pathway." (PMID 39136001, 2024). "ENC1, overlapping genes from CHIP-seq and RNA-seq, accelerated cervical cancer development by activating the ERK/MEK pathway." (PMID 38750489, 2024).
lung carcinoma (4 papers, 2022 to 2025). "In lung cancer cells transfected with si-ENC1, there was a significant decrease in N-cadherin expression and a marked increase in E-cadherin expression." (PMID 38177640, 2024). "In contrast to paracancerous tissues and normal lung cells, the expression of ENC1 was found to be significantly higher in lung cancer tissues and cells." (PMID 38177640, 2024). "Suppression of ENC1 expression inhibits the growth, migration and invasion of colon, breast, and lung cancer cell lines." (PMID 35818360, 2022). "ENC1, an actin-binding protein that is essential for gastrulation and nerve formation, has been reported to be overexpressed in the colon, breast, and lung cancers." (PMID 35818360, 2022). "Moreover, the knockdown of ENC1 significantly down-regulates the expression of mesenchymal markers (matrix metalloproteinase and N-cadherin) and up-regulates the expression of epithelial marker (E-cadherin) in lung cancer cell lines." (PMID 35818360, 2022). "In addition, levels of MMP-2, MMP9, N-cadherin, JNK, ERK, and p-p38 all decreased when ENC1 was turned off, indicating that si-ENC1 blocks the MAPK pathway, thereby preventing lung cancer cells from proliferating, migrating, and invading." (PMID 38177640, 2024).
brain tumors (3 papers, 2010 to 2021). "Normally, it has been ascribed to have roles in neuronal and adipocyte differentiation; however, the aberrant expression of ENC1 has been reported in human brain tumors including glioblastoma and astrocytoma." (PMID 33816464, 2021). "Mutations in ENC1 (KLHL37), also called NRP/B, are associated with brain tumors." (PMID 23676014, 2013). "Interestingly, ENC-1 is a nuclear matrix protein abundantly expressed in the brain and appears to be localized in primary neurons and is up-regulated in brain tumors, suggesting that it might be involved in brain tumorigenesis." (PMID 20515496, 2010).
glioblastoma (3 papers, 2009 to 2022). The most malignant astrocytic tumor (WHO grade IV). "ENC1 expression is increased in human brain cancers such as glioblastomas and astrocytomas, although it is normally limited to neurons." (PMID 36531950, 2022). "Upregulation of ENC1 has also been recorded in medulloblastoma, prostate, glioblastomas, and astrocytomas, indicating that the gene may have an oncogenic potential if inappropriately expressed." (PMID 33816464, 2021). "The exact role of other vascular genes such as PRCP, LIMS1 and ENC1 in glioblastoma is not clear yet, but given their expression pattern, an implication in tumor angiogenesis is possible and merits further investigation." (PMID 19924294, 2009).
melanoma (3 papers, 2011 to 2022). A malignant, usually aggressive tumor composed of atypical, neoplastic melanocytes. "The expression of ENC1 has been shown declined in melanoma cell lines and nervous system tumors." (PMID 35939448, 2022). "First, we can conclude that our MS approach allows detection of three HLA-A2 restricted neoepitopes presented on the melanoma cells (AGPS, ENC1, CCT4)." (PMID 31921104, 2019). "We identified four genes, PPP1R3C, ENC1, RARRES1 and TP53INP1 that were not previously known to be silenced by DNA methylation in melanoma." (PMID 22028813, 2011).
colon cancer (2 papers, 2012 to 2021). "Expression of ENC1 was examined in colon cancer samples and their corresponding non-cancerous tissues using semiquantitative RT-PCR, and its expression was increased in 17 of the 24 tumours analysed." (PMID 22280244, 2012).
endometrial carcinoma (2 papers, 2022 to 2024). A malignant tumor arising from the epithelium that lines the cavity of the uterine body. "In summary, ENC1 is a potential therapeutic target in endometrial carcinoma, and further research is needed to understand its precise role in promoting cancer progression and its interaction with the immune system in the TME." (PMID 38177640, 2024). "The expression of ENC1 was considerably upregulated in endometrial cancer tissues compared to adjacent normal endometrial tissues, as shown by western blot analysis of clinical samples." (PMID 36531950, 2022). "High expression of ENC1 in endometrial carcinoma suggests poor prognosis." (PMID 38177640, 2024). "Compared to normal endometrial cell lines, the mRNA expression of NR3C1 was dramatically lowered in endometrial cancer cell lines, whereas the mRNA expression of PKM2 and ENC1 was significantly upregulated." (PMID 36531950, 2022). "We discovered that the function of ENC1 in endometrial cancer has not been investigated, thus we employed western blot to investigate its expression further." (PMID 36531950, 2022).
hairy cell leukemia (2 papers, 2009 to 2024). Hairy cell leukemia (HCL) is a rare type of leukemia in which abnormal B-lymphocytes are present in the bone marrow, spleen and peripheral blood. "In tumor cells purified from patients suffering from hairy cell leukemia, ENC1 was significantly overexpressed in all the samples." (PMID 19424503, 2009).
leukemia (2 papers, 2010 to 2015). A malignant (clonal) hematologic disorder, involving hematopoietic stem cells and characterized by the presence of primitive or atypical myeloid or lymphoid cells in the bone marrow and the blood. "For example, ENC-1, often over-expressed in some types of leukemia, KLF12, a transcription factor associated with progression of gastric cancer, and CDC42EP2, a small Rho GTPase binding protein involved in hypoxia-induced angiogenesis, were induced by gefitinib at 24 h treatment." (PMID 20579378, 2010).
ovarian carcinoma (2 papers, 2022 to 2024). A malignant neoplasm originating from the surface ovarian epithelium. "Downregulation of ENC1 expression in ovarian cancer cells may lead to increased ROS production, which can cause oxidative stress, cellular damage, and dose-dependent growth inhibition." (PMID 38177640, 2024). "Low ENC1 expression has been linked to longer DFS and OS in ovarian cancer patients, and studies have shown that ENC1 expression is associated with FIGO stage in ovarian cancer." (PMID 38177640, 2024). "Therefore, ENC1 expression may be a useful predictor of ovarian cancer prognosis." (PMID 38177640, 2024).
adrenocortical adenomas (1 paper, 2020). "Ectodermal-neural cortex 1 is also overexpressed in adrenocortical adenomas." (PMID 33551826, 2020).